IDH1 (isocitrate dehydrogenase (NADP(+)) 1)
Diseases named in the same sentence as IDH1 in open-access papers (continued):
Sharing a sentence is not in itself a finding about the gene and the disease.
glioma (continued). "Our deep learning-based framework can detect and segment gliomas with excellent performance for the prediction of IDH-1 biomarker status and survival." (PMID 36139616, 2022). "Different cancers have mutations in IDH1 and IDH2, including a fraction of acute myeloid leukemia, low-grade glioma, secondary glioblastoma, chondrosarcoma, and cholangiocarcinoma." (PMID 35831624, 2022). "The elevated expression levels of COMMD4 accelerated the malignant progression of glioma, as evidenced by the IDH1-wildtype patients’ unfavorable survival." (PMID 36249824, 2022). "TBF and nTBF parameters in the wildtype glioma group were significantly higher compared to the IDH1-mutant glioma group (p < 0.001 for TBF and nTBF)." (PMID 35741254, 2022). "Accordingly, IDH1/2 mutations are a hallmark of lower-grade gliomas, up to 90% of WHO grade II and up to 70% of WHO grade III gliomas harboring mutations in these genes." (PMID 35806153, 2022). "Mutations in the gene encoding isocitrate dehydrogenase 1 (IDH1) and 2 (IDH2) were identified across several cancer types including gliomas, chondrosarcoma, and hematological malignancies." (PMID 35158978, 2022). "Recently, treatment of glioma with an IDH1-specific peptide vaccine has achieved 63% 3-year PFS and 84% 3-year OS among patients." (PMID 36350001, 2022). "Among these, AG221 (Enasidenib, CC90007; Agios) reported targeting IDH2 mutations and is currently beneath improvement to treat gliomas, in addition to AG881 (a pan-IDH1/-2 (Agios) inhibitor which is being developed for the administration of gliomas cancers." (PMID 35912242, 2022). "Inhibiting GLS in IDH1-mut glioma cells, in which 2-HG already suppresses BCAT, significantly impairs their fitness by lowering glutamate, glutathione, and resistance to oxidative stress in vitro and to radiation in vitro and in vivo." (PMID 35267433, 2022). "The expression of ZEB1 was enhanced in IDH1/2-mutant gliomas, and IDH1/2-mutant gliomas exhibited significantly lower values of ZEB1 protein." (PMID 36402997, 2022). "A recent study showed that mutant IDH1 gliomas downregulate the synthesis of phosphocholine and phosphoethanolamine in a 2-hydroxyglutarate-dependent manner." (PMID 35804936, 2022). "Previous studies have reported that IDH1 and IDH2 mutations were closely related to the prognosis of glioma patients." (PMID 35559020, 2022). "Mutations in isocitrate dehydrogenase 1 (IDH1) and IDH2 are oncogenic drivers to a variable extent in several tumors, including gliomas, acute myeloid leukemia (AML), cholangiocarcinoma, melanoma, and thyroid carcinoma." (PMID 34997121, 2022). "Nevertheless, the majority of adult gliomas that are of lower grades are IDH-mutant, so filtering using IDH1/2 mutation data reduced their number." (PMID 35877430, 2022). "We have previously reported that the IDH1-mutant mouse model of NCH1681 exhibits an active glycolytic pathway that yields lactate in vivo, similarly to other aggressive IDH1 mutant glioma models." (PMID 36353533, 2022). "Mutation can occur in the genes coding for either IDH1 or IDH2 genes, but in over 90% of infiltrating gliomas with IDH mutation, the detected variant is IDH1 R132H." (PMID 36397144, 2022). "IDH1 mutation (IDH1mut) is the most important genetic alteration in lower grade glioma, whereas glioblastoma (GB), the most common malignant brain tumor, often has wild‐type IDH1 (IDH1wt)." (PMID 34716958, 2022). "IDH1 mutations endowing the enzyme with such properties, for example IDH1-R132H, are found in a few types of human cancer, such as gliomas, acute myeloid leukemias, and osteosarcomas." (PMID 35628470, 2022).
glioma (continued). "This study investigated early volumetric, perfusion, and diffusion MRI changes in IDH1-mutant gliomas during IDH inhibitor treatment." (PMID 36033919, 2022). "A large number of previous research reports have presented that the expression level of BCAT1 plays a crucial role in the occurrence and development of IDH1 wild-type gliomas." (PMID 36119495, 2022). "This is because 13 patients (72.2%) had WHO grade 2 glioma, and 3 patients (16.7%) had WHO grade 3 glioma with isocitrate dehydrogenase 1 (IDH1) mutation, which progress slowly." (PMID 36347905, 2022). "A study treating patient-derived IDH1 mutant glioma xenografts, that demonstrate a specific CIMP profile of their own, with the 5-azacytidine demethylating agent has already shown tumor regression." (PMID 36455002, 2022). "The success of this approach in a preclinical setting was ascribed to IDH1-mutant gliomas having a CpG island methylator phenotype (CIMP) characterized by the robust and widespread methylation of CpG islands." (PMID 36230865, 2022). "IDH1 mutations at R132 have been associated with astrocytomas, GBM, and oligodendrogliomas, and IDH2 mutations at R172 have been linked with gliomas.IDH1/2 have been linked to enhanced reductive carboxylation in hypoxia for de novo lipogenesis." (PMID 36643416, 2022). "IDH1-mut glioma cells lowered NAD+ levels by silencing the NAD+ salvage enzyme nicotinic acid phosphoribosyltransferase (NAPRT) and are sensitive to the block of NAD+ biosynthesis via nicotinamide phosphoribosyltransferase (NAMPT) inhibition." (PMID 35267433, 2022). "More IDH1 mutations, 1p19q LOH and OD, and less GBM were found in CIMP-positive glioma than in CIMP-negative glioma." (PMID 36181110, 2022). "A mutant IDH1 glioma subgroup with codeletion of the chromosomal bands 1p and 19q as well as a mutation in the TERT promoter are histologically defined as oligodendrogliomas." (PMID 36276147, 2022). "In a phase I trial (NCT02454634) including 32 patients with grade III/IV glioma, approximately 90% of patients demonstrated an immune response after treatment with an IDH1-R132H+–specific vaccine." (PMID 36466873, 2022). "The maximum TBF in the IDH1-mutant glioma group (n = 58) was 73.35 ± 70.76 mL/100 g/min, nTBF was 4.06 ± 4.14—." (PMID 35741254, 2022). "This study aimed to investigate EZH2 immunoexpression in glioma patients and explore its clinical significance in tumour progression in relation to IDH1 R132H protein mutant status." (PMID 36292072, 2022). "A nomogram comprising gender, age, grade, IDH1 mutation, MGMT status, pq status, and risk score was created to predict OS in glioma tissues." (PMID 35903107, 2022). "The two enzymes converting glutamate to ɑ-KG, GLUD1, and GLUD2, are overexpressed in IDH1-mut tumors, and orthotopic growth of an IDH1-mut glioma line was inhibited by knockdown of GLUD1/2." (PMID 35267433, 2022). "Studies have examined the expression of PPAR-α protein and PPAR-α mRNA in primary wild-type human IDH1 GB, arguing that their overexpression in GB is related to the degree of glioma malignancy." (PMID 35203272, 2022). "The vast majority of IDH mutant gliomas harbor the arginine to histidine substitution at residue 132 of IDH1 (IDH1R132H)." (PMID 36303101, 2022). "Data exist on the effectiveness of these inhibitors on in vivo xenografts generated from IDH1-mutant gliomas and on xenografts generated from paediatric high-grade glioma samples." (PMID 36230865, 2022).
glioma (continued). "Intracellular NAD+ and NADPH+ levels were previously reported to differ in gliomas in a manner that was dependent on the IDH1 status." (PMID 35628596, 2022). "Although MGMT promoter methylation has limited diagnostic value, it is of great importance to guide treatment decisions on the use of chemotherapy with alkylating agents for patients with IDH1-wild-type gliomas and GBMs." (PMID 35372034, 2022). "Derived from this, this would mean that IDH-1 wild-type tumors, for instance, most higher-grade gliomas, would be more accessible for immunotherapy." (PMID 34687436, 2022). "The prognostic value of the combined immunoexpression of EZH2 and IDH1 was further explored in a retrospective analysis involving 56 patients with histologically confirmed gliomas in Universiti Kebangsaan Malaysia Medical Centre from 2010 to 2016." (PMID 36292072, 2022). "Testis-specific protein Y-encoded 2 (TSPYL2) was the top-hit gene most negatively correlated with IDH1 expression in the All gliomas and primary GBM analyses." (PMID 35877430, 2022). "Previously, our group validated this antibody on patient-derived glioma stem-like cells and on surgical specimens of glioma with mutant IDH1/2, in which we showed a co-staining of the tumor cells with anti-IDH1/2 and anti-CRMP5 antibodies." (PMID 35740509, 2022). "In glioma research, the increase of LOX protein expression is positively associated with the malignant grade of astrocytomas and GBM with IDH1 mutation always exhibits lower LOX expression levels compared with the wild type group." (PMID 36160460, 2022). "In IDH1-mt gliomas, lower levels of fatty acyl chains, triglycerides and sphingolipids are posited to be due to low acyl-CoA synthetase 1which has conferred better survival outcomes." (PMID 36643416, 2022). "Glioma patients with wild-type IDH1, mutant EGFR or mutant PTEN showed higher expression of SLC11A1 than those with other phenotypes." (PMID 36531992, 2022). "Mutations in isocitrate dehydrogenase 1 (IDH1) and IDH2 drive the development of gliomas, which occur in most low-grade gliomas and secondary high-grade gliomas, and they enable the isocitrate dehydrogase (NADP+) activity." (PMID 36561336, 2022). "Perhaps the most established examples are the mutations found in in Isocitrate Dehydrogenase 1 (IDH1) and IDH2 that cause a major subset of gliomas." (PMID 35379950, 2022). "The IDH1 R132C variant has been recorded in a COSMIC database for the blood and lymphatic system tumors, bone tumors, central nervous system tumors, biliary tumors, and other tumors (Genomic Mutation ID: COSV61615256)." (PMID 35765075, 2022). "The expression of mediators, effectors and targets of the canonical WNT pathway, including β-catenin, TCF4 and LEF1 is downregulated in glioma cells overexpressing IDH1-R132H." (PMID 34070746, 2021). "To further detecting B7H3 and VEGFA expression levels in human glioma specimens, we randomly picked out 9 of 2-HGhigh, 8 of 2-HGlow, and 4 IDH1-WT glioma samples to conduct IHC staining for B7H3 and VEGFA." (PMID 34079802, 2021). "Tumor-associated factors include tumor grade (HGG vs LGG) and tumor size greater than 5 cm, subtotal surgical resection as compared with total resection, intraluminal thrombosis in the surgical specimen, recurrent disease, and IDH-1 wildtype glioma." (PMID 33828976, 2021). "Each parameter was compared between IDH1-mutant and IDH1 wild-type groups by Mann–Whitney U test in lower-grade gliomas (LrGGs) and glioblastomas (GBMs), respectively." (PMID 34880724, 2021). "Meanwhile, the glucose quantity in IDH1mutant glioma samples were significantly lower than those in IDH1 wild-type tissues (1.033 ± 1.19608 vs 6.361 ± 4.3909 mg/g, P = 0.0051)." (PMID 33472598, 2021).
glioma (continued). "To conclude, our work highlights that high expression of BCAT1 is a sensitive marker for predicting poor prognosis of IDH1 wild-type glioma patients." (PMID 33493139, 2021). "The aim of this study was to determine how glutathione (GSH), the main antioxidant in the brain, is maintained in IDH1-mutant gliomas, despite an altered NADPH/NADP balance." (PMID 34250481, 2021). "The result suggested that for patients with IDH1 mutant gliomas, more attention and closer monitoring for seizure should be given during postoperative follow-up even if they did not have preoperative GRE, and long-term AED prophylaxis is potential helpful." (PMID 34220689, 2021). "This approach is based on the evidence that glioma patients developed a Th-1 response against IDH1(R132H)+ tumours." (PMID 34070384, 2021). "One of the most central genetic characteristics is the isocitrate dehydrogenase mutation (IDH1) status that is commonly expressed in low-grade gliomas and reflects a favorable prognosis relative to IDH1 wild-type gliomas that are high-grade glioblastomas." (PMID 34440802, 2021). "Multivariate Cox analysis revealed that ARL score, age, grade, and IDH1 status were independent protective factors for glioma patients." (PMID 34211979, 2021). "In this study, HOXB7 was highly expressed in GBM and IDH1 wild type gliomas at both mRNA and protein levels." (PMID 34458259, 2021). "We believe that with the current Pan-Cancer Analysis of Whole Genomes (PCAWG) project involving classic glioma microenvironment biomarkers (i.e., IDH1), researchers will identify more specialized features of cancer immune genomes." (PMID 34220791, 2021). "In U251 glioma cells, expression of mutIDH1 or treatment of WT IDH1 cells with exogenous R-2-HG leads to a reduction in the pro-proliferative effects of GABA." (PMID 35028610, 2021). "In IDH1-mutant gliomas, R-2-hydroxyglutarate (R-2-HG) significantly decreases the antigen-presenting signature in macrophages and induces an immunosuppressive phenotype." (PMID 34646780, 2021). "It has recently been reported that in response to 2-HG inhibition, the PD-L1 levels in IDH1 mutant tumors were increased to the same levels observed in WT-IDH gliomas." (PMID 34298712, 2021). "In different grades of glioma, patients with isocitrate dehydrogenase 1 (IDH1) mutant glioma had significant prolonged OS compared with IDH1 wildtype ones." (PMID 34211979, 2021). "Overall, these data suggest BCAT1 is correlated with the immunosuppressive signature of IDH1 wild-type gliomas." (PMID 33493139, 2021). "This study found that mutant IDH-1 gliomas have a decreased platelet activity and increased antithrombotic activity with less common microthrombi within IDH-1 mutant gliomas." (PMID 34178693, 2021). "One study reported that TNFRSF12A promoted the invasive phenotype of IDH1 wild-type gliomas, while IDH1-mutant gliomas exhibited low TNFRSF12A mRNA and protein levels compared with IDH1 wild-type gliomas." (PMID 33937046, 2021). "It has been shown that patients with IDH1 and IDH2 mutated gliomas have better survival rates than patients with IDH wild type tumors." (PMID 34557149, 2021). "In particular, IDH1/2 gene mutations are found in more than 70% of grade II-III glioma and secondary GBM that arises from low-grade glioma." (PMID 34461927, 2021). "Point mutations in both IDH1 and IDH2 have been frequently associated in the pathogenesis of a subset of gliomas, mainly low-grade gliomas and secondary glioblastomas." (PMID 34884868, 2021). "Even many molecular characteristics of gliomas such as the combined deletion of 1p/19q, IDH1 mutations, and hypermethylation of the MGMT promoter are expected to be detected in circulating tumor cells in peripheral serum of glioma patients." (PMID 33777749, 2021).
glioma (continued). "A subgroup of adult-type diffuse mutant IDH1 gliomas which harbor 1p/19q chromosomal co-deletions (1p/19q-codel) and TERT promoter mutation are now classified as oligodendrogliomas." (PMID 34422657, 2021). "In high TNFSF13 gliomas, somatic mutation was proved to correlate with amplification of EGFR and deletion of CDKN2A; while mutation of IDH1 was more frequently observed in low TNFSF13 group." (PMID 34712225, 2021). "Addition of MR diffusion to conventional MRI features provides added diagnostic value in preoperative determination of IDH1, MGMT, and ATRX in patients with glioma." (PMID 34056604, 2021). "Next, we examined the protein level of B7H3 in fresh glioma tissues and found that the protein expression of B7H3 was significantly reduced in IDH1-R132H gliomas (n = 11) compared to that in IDH1-WT gliomas (n = 11, p < 0.05)." (PMID 34079802, 2021). "We also analyzed the expression of CRYAB (alpha-B crystallin) as this protein was described to be elevated up to 22-fold in IDH1-mutant gliomas." (PMID 33925547, 2021). "Results showed that, in patients with IDH1 wild-type, as the histologic tumour grade increased, the onset age of glioma was increased." (PMID 34205437, 2021). "A study for gliomas patients by detecting of IDH1, TERT, and H3K27M also showed high detection sensitivity (71%, 20 out of 28) and specificity." (PMID 34603383, 2021). "The detection of 2HG by MRS can aid in the diagnosis of rare, non-IDH1-R132H IDH1 and IDH2 mutations in gliomas." (PMID 34829476, 2021). "Actually, IDH1/2 status and the ME transition of glioma cell inevitably affect the components of tumor immune microenvironment, especially the components of lymphocytes." (PMID 34830775, 2021). "In conclusion, we identified a high incidence of IDH1 and IDH2 mutations in a tissue-specific manner most notably in gliomas, and various types of skin cancer suggesting a potential role in the pathogenesis of these solid malignancies." (PMID 35996504, 2021). "Isocitrate dehydrogenase 1 (IDH1) mutation, which occurs early in gliomagenesis particularly in WHO grade II and III gliomas, is an acknowledged molecular alteration." (PMID 34458259, 2021). "The presence of mutant forms of isocitrate dehydrogenase 1 (IDH1) is a key factor in determining the prognosis of patients with gliomas." (PMID 34733261, 2021). "Several studies from us and others have shown that DNMT1 inhibitors, decitabine (DAC) and azacitidine (AZA), exerts an antiproliferative tumor effect in vitro and in vivo in IDH1-mutant gliomas." (PMID 34067729, 2021). "The discovery of IDH1 and IDH2 mutations led to a biomarker defined classification of gliomas based on prognosis and treatment response." (PMID 34597473, 2021). "Isocitrate dehydrogenase 1/2 (IDH1/2) mutations occur at 70% of grade II and III gliomas as an early event with better prognostic survival." (PMID 34194624, 2021). "IDH1 and BRAFV600E mutations are associated with infiltrative gliomas or circumscribed gliomas and glioneuronal tumors, respectively, and they are exclusive in most cases." (PMID 33980169, 2021). "An alternative decision tree starting with IDH1-R132H staining identified 50/69 IDH1-R132H-positive gliomas that showed ATRX nuclear retention and that required 1p/19q testing to identify 39 oligodendrogliomas." (PMID 34020723, 2021). "Our analysis of cancer data from The Cancer Genome Atlas revealed a high incidence of IDH1 and IDH2 mutations in subtypes of gliomas." (PMID 35996504, 2021).